NTHL1 (nth like DNA glycosylase 1)
Diseases named in the same sentence as NTHL1 in open-access papers (continued):
Sharing a sentence is not in itself a finding about the gene and the disease.
breast carcinoma (17 papers, 2019 to 2024). "An increased risk for colorectal and breast cancer typically characterizes biallelic mutations in NTHL1." (PMID 36979978, 2023). "Although the total number of tumors analyzed remains small, the NTHL1-het tumors appeared similar to sporadic breast cancers in regard to the somatic mutational features, and in other respects (HRD scores, histopathology, and FGA)." (PMID 33980861, 2021). "We have examined this possibility specifically in regard to the risk of breast cancer through sequencing of a large number of cases and controls and examination of the somatic landscape of cancers occurring in women carrying a single NTHL1 LoF variant." (PMID 33980861, 2021). "A predominant mutational signature SBS30 was observed in the NTHL1-null breast cancer, consistent with the previously reported NTHL1 bi-allelic loss driving tumorigenesis mechanism." (PMID 33980861, 2021). "In summary, this is the first study to investigate the role of heterozygous NTHL1 LoF and missense variants in breast cancer predisposition, which included 47,180 subjects from ten international case-control studies." (PMID 33980861, 2021). "No additional bi-allelic LoF variants were identified in subjects of the validation dataset, indicating germline bi-allelic loss of NTHL1 is extremely rare as a cause of breast cancer (1/27,421 breast cancer cases and 0/19,759 controls)." (PMID 33980861, 2021). "Histopathologic characteristics are summarized for 22 breast cancers from 20 NTHL1 LoF variant carrier cases in the BEACCON study where pathology information was available." (PMID 33980861, 2021). "Somatic sequencing of breast cancers from carriers indicated that the risk associated with NTHL1 appears to operate through haploinsufficiency, consistent with other described low-penetrance breast cancer genes." (PMID 33980861, 2021). "Co-segregation analysis of breast cancer in families was performed in 16 multi-case families from the BEACCON study segregating NTHL1 LoF variants where detailed pedigree information was available." (PMID 33980861, 2021). "An analysis of 4985 women with breast cancer, enriched for familial features, and 4786 cancer-free women revealed significant enrichment for NTHL1 LoF variants." (PMID 33980861, 2021). "In the currently analyzed cohorts, heterozygous NTHL1 p.Q90* carriers were identified in 2.1% cases with indication of hereditary predisposition to disease and in 1.0% of the breast cancer cases unselected for family history or age at disease onset." (PMID 32949222, 2020). "Here, we have tested the prevalence of NTHL1 nonsense variant c.268C>T, p.Q90*, which is the major allele in NTHL1 families and also shows enrichment in the Finnish population, in a total of 1333 breast cancer patients." (PMID 32949222, 2020). "This geographical enrichment provides an excellent opportunity to test the association of NTHL1 p.Q90* with breast cancer susceptibility at the population level, along with the potential to establish risk estimates for the allele at heterozygous state." (PMID 32949222, 2020). "The first cases of a PALB2, an APC and a NTHL1 pathogenic variants in patients with both breast cancer and NET were presented." (PMID 31592449, 2019). "Sample PD31203a showed a mutational signature (signature 30) that strongly matched the base excision repair NTHL1 deficiency pattern, previously only seen in a breast cancer and an osteosarcoma." (PMID 30889380, 2019). "Application of this approach to the cancer predisposition gene NTHL1 demonstrated that a high contribution of a mutational footprint (signature 30), observed in a breast cancer cohort, within a tumour can be indicative of germline mutations in NTHL1." (PMID 31282586, 2019).
breast carcinoma (continued). "One signature originally identified in human breast cancer, referred to as Signature 30, was found to be similar to that found following NTHL1 gene deletion, suggestive that “signature 30” may arise from NTHL1 gene mutations." (PMID 34198612, 2021). "Data from this very large international multicenter study suggests that heterozygous pathogenic germline coding variants in NTHL1 may be associated with low- to moderate- increased risk of breast cancer." (PMID 33980861, 2021). "Bi-allelic loss-of-function (LoF) variants in the base excision repair (BER) gene NTHL1 cause a high-risk hereditary multi-tumor syndrome that includes breast cancer, but the contribution of heterozygous variants to hereditary breast cancer is unknown." (PMID 33980861, 2021). "In addition, whole-genome and targeted sequencing was performed on formalin-fixed, paraffin-embedded (FFPE)-derived DNA from the breast cancers of 20 germline NTHL1 LoF variant carriers." (PMID 33980861, 2021). "Although there is strong evidence for breast cancer being a part of the cancer spectrum in these families, the role of pathogenic NTHL1 variants in breast cancer susceptibility in general population remains unclear." (PMID 32949222, 2020). "Similar carrier frequencies between studied cases and the general population argue against association of NTHL1 p.Q90* in a heterozygous state with increased breast cancer risk, although we acknowledge that the sample size of hereditary cohort is limited to 234 cases." (PMID 32949222, 2020). "Although there is strong evidence for breast cancer being a part of the cancer spectrum of recessively inherited NTHL1 tumor syndrome, the role of pathogenic NTHL1 variants in breast cancer susceptibility in the general population remains unclear." (PMID 32949222, 2020). "We tested the prevalence of NTHL1 nonsense variant c.268C>T, p.Q90*, which is the major allele in NTHL1 families and also shows enrichment in the Finnish population, in a total of 1333 breast cancer patients." (PMID 32949222, 2020). "The NTHL1 gene was said to be causative of multiple cancers, including breast cancer." (PMID 31870441, 2019). "A multivariable logistic regression model was used to simultaneously evaluate the association of NTHL1 LoF variants, missense variants, and the PRS with breast cancer in the case–control cohort." (PMID 33980861, 2021). "Since CpG island methylation in the promoter region is a possible alternative mechanism of gene silencing, bisulfite sequencing was performed across the NTHL1 promoter region for 13 breast cancers with sufficient DNA available." (PMID 33980861, 2021). "Although the relationship between (familial) breast cancer and colorectal cancer is a controversial subject, recently, it was discovered that rare mutations in the NTHL1 gene, which was originally associated with CRC, also cause breast cancer." (PMID 34299028, 2021). "All exons and exon-intron boundaries of the NTHL1 gene were sequenced in the BEACCON study of index cases from 4985 hereditary breast cancer families and 4786 cancer-free female controls from the same Australian population." (PMID 33980861, 2021). "In total, the frequency of NTHL1 p.Q90* in the studied breast cancer cohorts (16/1333, 1.2%, p = 0.61, OR = 0.8, 95% CI = 0.4–1.6) did not significantly differ from the population frequency (19/1324, 1.4%) in this geographical region." (PMID 32949222, 2020). "In the unselected breast cancer cohort, 11 NTHL1 p.Q90* carriers were identified (11/1099, 1.0%, p = 0.36, OR = 0.7, 95% CI = 0.3–1.5)." (PMID 32949222, 2020).
breast carcinoma (continued). "In these families, two additional breast cancer cases (family members of Her3 and Her4, respectively) were available for testing and one of them (breast cancer at the age of 62 years) was identified to carry NTHL1 p.Q90*." (PMID 32949222, 2020). "In our prediction list, NTHL1, which encodes a functional DNA N-glycosylase of endonuclease III family, has been predicted to have differential methylation status in various breast cancer subtypes." (PMID 31480430, 2019). "Biological SBS30 occurs more rarely: it is caused by loss-of-function in glycosylases in BER due to biallelic inactivation mutations in NTHL1, and patients carrying this variant are with an increased lifetime risk for CRC, breast cancer, and colorectal polyposis." (PMID 36068219, 2022). "The one NTHL1-null breast cancer also showed a very low FGA and HRD score (0.07 and 7)." (PMID 33980861, 2021). "Our results indicate that NTHL1 p.Q90* heterozygous carriers do not have an increased risk for breast cancer and that the variant is unlikely to be a significant contributor to breast cancer risk at the population level." (PMID 32949222, 2020). "Frequency of NTHL1 p.Q90* (c.268C>T)a in the studied breast cancer cohorts and controls." (PMID 32949222, 2020). "For this purpose, here, we have tested the prevalence of NTHL1 p.Q90* in breast cancer patients with an indication of hereditary disease susceptibility and those unselected for the family history of cancer and age at disease onset, all collected from the North Ostrobothnia area." (PMID 32949222, 2020). "In line with the absence of bi-allelic inactivation, the three NTHL1-het breast cancers each exhibited a mixture of mutational signatures, with the top contributing signatures including COSMIC signatures SBS3, SBS5, and SBS16, similar to the sporadic breast cancers." (PMID 33980861, 2021). "The data suggest that NTHL1 may be associated with a modest increase in breast cancer risk that would not be considered clinically actionable in isolation under current clinical guidelines but could be relevant when combined with additional risk factors." (PMID 33980861, 2021). "In conclusion, the current results indicate that NTHL1 p.Q90* allele is unlikely to be a significant contributor to breast cancer risk at the population level and that the risk is not increased in heterozygous carriers, which is in line with results obtained from other cancer types." (PMID 32949222, 2020). "Our results indicate that NTHL1 p.Q90* heterozygous carriers do not have an increased risk for breast cancer and that the variant is unlikely to be a significant contributor to breast cancer risk at the population level, a notion that is particularly important for genetic counseling." (PMID 32949222, 2020). "Previous studies have reported that several genes, such as NTHL1, ZCCHC24, and SNX1b, have different methylation status in different subtypes of breast cancer." (PMID 32633782, 2020). "Tumor sequencing and promoter methylation analyses demonstrated that NTHL1 does not undergo bi-allelic inactivation in breast cancers, which is supported by the fact that NTHL1-het tumors retain approximately 50% of the wildtype protein expression." (PMID 33980861, 2021).
tumor syndrome (14 papers, 2020 to 2024). "To date, 201 NTHL1 germline variants have been associated with NTHL1 tumor syndrome, more than half of which are VUSs." (PMID 39195204, 2024). "In the NTHL1 tumor syndrome, the altered gene is NTHL1 (Nth Like DNA Glycosylase 1), encoding a DNA N-glycosylase (endonuclease III family) involved in base excision repair (BER)." (PMID 37239385, 2023). "The c.244C>T variant (previously reported as c.268C>T p.(Gln90Ter)) is the most frequent LoF variant identified in the patients with NTHL1 tumour syndrome as well as in the NTHL1 gene in the gnomAD database." (PMID 38036545, 2023). "As only few families with NTHL1 tumor syndrome had been reported in the literature, the mutation pattern in different populations is still poorly established." (PMID 37727376, 2023). "NTHL1 tumor syndrome is an autosomal recessive rare disease caused by biallelic inactivating variants in the NTHL1 gene and which presents a broad tumor spectrum." (PMID 37727376, 2023). "On the other hand, we identified two index patients and several relatives from NTHL1 tumor syndrome families who are heterozygous for pathogenic variants in the NTHL1 gene." (PMID 37727376, 2023). "Recent papers highlighting the now apparent extended tumour phenotype seen in individuals’ with two NTHL1 mutations suggest NTHL1 tumour syndrome as a more accurate name for this condition." (PMID 33948826, 2022). "Biallelic NTHL1 mutations are responsible for the NTHL1-tumor syndrome, a cancer-predisposing disease characterized by the occurrence of adenomatous polyposis and cancer at different sites, in addition to CRC." (PMID 35534873, 2022). "The known autosomal recessive adenomatous polyposis syndromes are MUTYH-associated polyposis (MAP) and NTHL1 associated tumor syndrome." (PMID 32258104, 2020). "Phenotypic characterization of additional families will increase the knowledge of tumor spectrum and cancer risk in association with NTHL1-associated tumor syndrome." (PMID 32258104, 2020). "In the NTHL1-associated tumor syndrome, an association between base excision repair defects and specific somatic mutation signature in adenomas is found." (PMID 32258104, 2020). "Patients with NTHL1 tumor syndrome exhibit many tumors, all clinically associated with polyposis." (PMID 39195204, 2024). "In this study, we tested two consecutive series of patients, one with colorectal polyposis and the other with familial/personal history of multiple tumors (besides multiple breast/ovarian/polyposis), in order to contribute to characterization of NTHL1 tumor syndrome associated phenotype." (PMID 37727376, 2023). "In this syndromes group, we could find Ataxia telangiectasia, PSJ, FA, Polymerase proofreading-associated polyposis, NTHL1 tumor syndrome, CS, HDGC, MLH3-associated polyposis, NF1, MEN1, LF, and BSyn." (PMID 37239385, 2023). "Other genes such as RPS20 (associated with MMR-proficient, non-polyposis CRC; RPS20-associated hereditary CRC) and NTHL1 (associated with polyposis hereditary CRC; NTHL1-tumor syndrome) are less prevalent and may be added to CRC NGS panels." (PMID 37965459, 2023). "NTHL1 tumor syndrome, a recently identified rare autosomal recessive polyposis, is caused by biallelic variations in the NTHL1 gene." (PMID 39195204, 2024). "Biallelic mutations in NTHL1 predispose individuals to polyposis, CRC, and numerous other tumor types, earning it the name NTHL1-associated tumor syndrome." (PMID 39057027, 2024). "NTHL1 tumor syndrome (NTS) is an autosomal recessive genetic condition." (PMID 35967160, 2022).
adenoma (8 papers, 2013 to 2025). A neoplasm arising from the epithelium. "The second case was a 71-year-old patient with 20 adenomas and the mutation c.268C > T p.(Gln90Ter) in NTHL1 gene, in homozygosis." (PMID 39661238, 2025). "The NTHL1 rs2516781 SNP was associated with a two-fold decreased risk of adenoma only among Asian-Pacific Islanders." (PMID 23951112, 2013). "Firstly, although SBS30 was shown to be a predominant mutational signature in adenomas from biallelic NTHL1 cases, our results showed variable presence of SBS30 in two serrated polyp subtypes, 69.4 % in the traditional serrated adenoma and only 6.2 % in the hyperplastic polyp." (PMID 39793275, 2025). "In addition to 7 adenomas and 2 CRCs, a hyperplastic polyp and a traditional serrated adenoma from two biallelic NTHL1 cases (Pat_005 and Pat_469) were tested." (PMID 39793275, 2025). "The presence of ≤10 adenomas in several mutation carriers suggests a possible causal role of NTHL1 in hereditary or early-onset nonpolyposis CRC." (PMID 31227763, 2019). "SBS18+SBS36 and SBS30 were enriched in adenomas at comparable proportions to those observed in CRCs from biallelic MUTYH and biallelic NTHL1 cases, respectively." (PMID 39793275, 2025). "Similarly, in biallelic NTHL1 cases, SBS30 signature proportions in adenomas (74.5 %±9.4 %) were similar to those in CRCs (78.8 % ± 2.4 %) but significantly higher compared with non-hereditary adenomas (2.8 % ± 3.6 %, p-value=5.1 × 10–7)." (PMID 39793275, 2025). "Therefore, we discarded the involvement of the NTHL1 monoallelic mutation c.268C > T p.(Gln90*) in the polyposis predisposition of this patient and we considered the possibility that POLE:c.141delG p.Phe48Leufs*6 could confer the adenoma predisposition by itself." (PMID 31285513, 2019). "Our findings suggest that biallelic mutations in NTHL1 rarely cause CRC, a personal/familial multi-tumor history, or serrated polyposis, in absence of adenomas." (PMID 31227763, 2019). "Whole-exome sequencing of FFPE tissue and matched blood-derived DNA was performed on 9 adenomas and 15 CRCs from 13 biallelic MUTYH cases, on 7 adenomas and 2 CRCs from 5 biallelic NTHL1 cases and on 27 adenomas and 26 CRCs from 46 non-hereditary (sporadic) participants." (PMID 39793275, 2025). "This study provides important findings demonstrating that testing adenomas for SBS18+SBS36 or SBS30 can be an equally effective alternative to identifying biallelic MUTYH or biallelic NTHL1 cases, respectively, if CRC has not yet developed or tissue is not available." (PMID 39793275, 2025). "However and unlike POLE, NTHL1 expression was increased in two of the carrier’s adenomas and adenocarcinoma tissues." (PMID 31285513, 2019).
colorectal polyposis (7 papers, 2015 to 2026). "Biallelic pathogenic variants of NTHL1 are associated with colorectal polyposis and with breast and endometrial cancers." (PMID 41214301, 2026). "While predisposing variants in genes such as NTHL1, MSH3, POLE, POLD1, DSC2, and PIEZO1 have been associated with colorectal polyposis, they do not fully mimic the classical FAP phenotype." (PMID 41204315, 2025).
Familial adenomatous polyposis (7 papers, 2016 to 2025). Familial adenomatous polyposis (FAP) is characterized by the development of hundreds to thousands of adenomas in the rectum and colon during the second decade of life. "The NTHL1 gene is associated with familial adenomatous polyposis and hereditary cancer predisposition syndrome, with an autosomal recessive inheritance pattern." (PMID 40458721, 2025). "Biallelic mutations in the human ortholog of NTG1, NTHL1, are a high-risk factor for familial adenomatous polyposis." (PMID 37738679, 2023). "First, we searched for deleterious variants in the genes associated with adenomatous polyposis of the colon (APC, MUTYH, NTHL1, POLD1, and POLE)." (PMID 27217144, 2016). "This group includes familial adenomatous polyposis, attenuated familial adenomatous polyposis, MUTYH-associated polyposis, NTHL1-associated polyposis, Peutz–Jeghers syndrome, juvenile polyposis syndrome, Cowden syndrome, Lynch syndrome, and Muir–Torre syndrome." (PMID 36553592, 2022). "People with polyposis could have a genetic basis with germline mutations in polyposis-related genes, such as the APC gene, resulting in familial adenomatous polyposis (FAP), MUTYH-associated polyposis (MAP), or, rarely, in other genes such as AXIN2, GREM1, NTHL1, POLE, POLD1, or MSH3." (PMID 40095498, 2025).
mutyh-associated polyposis (6 papers, 2017 to 2023). An autosomal recessive hereditary neoplastic syndrome caused by mutations in the MUTYH gene on chromosome 1p34.1. "Hereditary syndromes (MUTYH-associated polyposis, NTHL1-associated tumor syndrome) with germline mutations causing a loss-of-function in base excision repair glycosylases, serve as straight forward evidence on the role of oxidative DNA damage and its repair." (PMID 35628513, 2022).